CCND1 (cyclin D1)
Diseases named in the same sentence as CCND1 in open-access papers (continued):
Sharing a sentence is not in itself a finding about the gene and the disease.
breast cancer (continued). "In addition, since earlier studies on patients with breast cancer reported the role of the combination of PAK1 and CCND1 expressions as a predictor of recurrence-free survival, the relationship between PAK1 alone and the recurrence-free survival rate is unclear." (PMID 33261184, 2020). "The lncRNA BCAR4 (breast cancer anti-estrogen resistance 4), originally identified in breast cancer, has been described to directly interact with and stabilize β-Catenin protein, which enhances the expression of Wnt target genes, such as MYC and CCND1, by preventing β-Catenin degradation." (PMID 33352769, 2020). "Knockdown of fascin (fascin−) in basal-like triple-negative MDA-MB-231 breast cancer cells, which are naturally fascin positive (fascin+), significantly (p < 0.05) reduced the protein expression of β-catenin, as well as TCF3 and cyclin D1, known β-catenin targets." (PMID 32373510, 2020). "Zhang et al43 reported the lack of CCND1 was associated with a compensatory upregulation of CCND3 and the inhibition of both CCND1 and CCND3 could be a suitable strategy for breast cancer prevention and therapy." (PMID 30950241, 2019). "There was a negative correlation between LINC01355 and CCND1 expression in breast cancer samples." (PMID 31243265, 2019). "To elucidate the molecular mechanism whereby conditioned macrophages affect ERα+ breast cancer cells and induce estradiol-independent proliferation via TNF-α stimulation, we used chromatin cross-linking and ChIP assays to identify assembled protein complexes that operate on cyclin D1." (PMID 30736340, 2019). "It is worth noting that all of these genes except PGR (P<0.05) and CCND1 (P<0.01) which were down-regulated, were up-regulated in ER+ MCF-7 cells by 4-OH-TAM, confirming their pathophysiological relevance and possible involvement in mediating the anti-breast cancer effects of TAM." (PMID 29416786, 2018). "Though decreased CCND1 activity may block proliferation, low CCND1 has been shown to correlate with high ID1 levels, as seen in the 20 mm region, which may promote more aggressive breast cancer tumor phenotype and metastasis." (PMID 30325954, 2018). "Whether other proliferation markers, like Cyclin D1, and mitotic count can also be used to identify those estrogen receptor α (ERα) positive breast cancer patients that derive benefit from tamoxifen is not well established." (PMID 30041599, 2018). "However, cyclin D1 is overexpressed at the protein levels in ~50% of breast cancers in the presence or absence of gene amplification." (PMID 30018827, 2018). "It has also been described that metformin-induced cell cycle arrest is mediated by cyclin D1 inhibition and Rb dephosphorylation in prostate cancer cells or by an AMPK-dependent mechanism requiring the downregulation of cyclin D1 and implication of p21 and p27 in breast cancer cells." (PMID 30186236, 2018). "Furthermore, AGR2 has been shown to promote cell cycle progression via induction of cell cycle proteins such as cyclin D1, and extracellular AGR2 knockdown using anti-AGR2 antibodies in three ER+ breast cancer cell lines significantly reduces cyclin D1 protein levels and cell growth." (PMID 29796176, 2018). "Cyclin D1 and collagen VI have previously been described as negative prognostic biomarkers, and their overexpression has been suggested as a possible molecular driver in breast cancer." (PMID 29108297, 2017). "In this study, we found that cfDNA from breast cancer cells not only could activate the TLR9-NF-κB pathway, but also increased the amount of p-ERα in HR+ breast cancer cells, ultimately increasing the abundance of cyclin D1." (PMID 28574818, 2017). "However, in the ER-positive group, high cyclin D1 expression had a significant and strong negative effect on breast cancer mortality in both univariable (OR 3.2) and multivariable (OR 3.1) analyses." (PMID 28528450, 2017). "Amplification of GAB2, independent of CCND1, has been observed in breast carcinoma samples." (PMID 28391240, 2017).
breast cancer (continued). "Additionally, while not necessary for normal mammary gland development, CDK4 and cyclin D1 are required for induction of breast malignancies in mouse models, suggesting that CDK4 inhibition may inhibit breast cancer cells while sparing healthy tissues." (PMID 26857361, 2016). "Concordantly, the expression levels of multiple downstream targets of Wnt/β-catenin signaling, namely cyclin D1, c-MYC, TCF4 and LEF1, and nuclear β-catenin, were increased in the miR-1229–overexpressing breast cancer cells but decreased in the miR-1229–silenced breast cancer cells." (PMID 26992223, 2016). "This study reports that rat mammary tumors induced with the AhR-agonist 7,12-dimethyl-benzo(a)anthracene (DMBA) had augmented CpG methylation of the Brca-1 gene; higher expression of Ahr, Cyp1b, and proliferation markers (Cdk4, Ccnd1); and diminished expression of BRCA-1 and ERα." (PMID 26715507, 2015). "Therefore, we conclude that CCND1, which belongs to the components of CDK2 and the downstream molecules of HER-2 signaling in Breast Cancer signaling pathway, could promote G1 phase of NIH3T3 by participating in the synthesis and degradation of protein." (PMID 26511608, 2015). "Since β-catenin is a common regulator of RUNX2 and cyclin D1, and its expression correlates with ER-β receptors in breast cancer cells, it may be considered as another important element of RUNX2-related pathways in breast cancer development." (PMID 26404249, 2015). "Results from this study also highlight the importance of HER-2/neu or PI3K/Akt components, including GSK-3β, β-catenin, cyclin D1 and p21WAF1, which may serve as future targets for the development of therapeutic strategies against HER-2/neu-overexpressing breast cancer." (PMID 24765191, 2014). "However, direct interaction exists only between cyclin D1 and ERα rather than Bmi1, and the expression of cyclin D1 in breast cancer probably reflects the regulatory effect of ERα." (PMID 24559156, 2014). "Furthermore, cyclin D1 is an essential component for carcinogenesis in some cancers, which is supported by the fact that cyclin D1 knockout mice do not make mammary carcinomas in spite of the overexpression of c-neu and v-Ha-ras." (PMID 24618206, 2014). "Interestingly, we found previously that PLAC1 is a critical factor for breast cancer progression, as RNAi-mediated silencing of PLAC1 in MCF-7 and BT-549 breast cancer cells results in decreased cyclin D1 levels and induces a G1-S cell cycle block with nearly complete abrogation of proliferation." (PMID 24304549, 2013). "Moreover, immunoblot analysis showed increased p27 expression but decreased levels of cyclin D1 or cyclin E in breast cancer cells that lacked BRG1." (PMID 23533649, 2013). "Additionally, the ability of constitutive CCND1/CDK2 activity to replace MYC over-expression is consistent with gene amplification data in clinical breast cancer specimens that show CCND1 and MYC are not typically co-amplified." (PMID 23390492, 2013). "Our analysis of a breast cancer dataset finds that the positive feedback loops across 7 genes, AR, ESR1, MYC, E2F2, PGR, BCL2 and CCND1 are conserved across the basal/triple negative subtypes in multiple datasets that could potentially explain the aggressive nature of this cancer subtype." (PMID 23368093, 2013). "Unlike CCND1 amplification, RSF1 amplification may predict for outcome in high-risk premenopausal breast cancer patients treated with adjuvant tamoxifen." (PMID 24367492, 2013). "Our results also highlight the importance of HER-2/neu or PI3K/Akt components, including GSK-3β, β-catenin, cyclin D1, Cdk4, p21WAF1, and p27KIP1, which may serve as future targets for the development of therapeutic strategies against HER-2/neu-overexpressing breast cancer." (PMID 22701509, 2012). "In addition, cyclin D1 is known to be expressed at variable levels across cell lines and subtypes of breast cancer thus, silencing of cyclin D1 is unlikely to increase migration uniformly in all cell types." (PMID 21955753, 2011).
breast cancer (continued). "Cyclin E1 is often expressed at high levels in the absence of increased cyclin D1, and in fact cyclin E1-Cdk2 activity is increased by estrogen in breast cancer cells primarily through disengagement of p21Waf1/Cip1 rather than transcriptional upregulation by cyclin D1." (PMID 20180967, 2010). "However, our results suggest that auraptene may reduce cell proliferation through the suppression of cyclin D1 in MCF-7 cells and in the rat mammary tumors." (PMID 19640308, 2009). "Furthermore, cyclin D1 is thought to mediate cell proliferation by different mechanisms in estrogen receptor positive and negative breast cancer." (PMID 19615042, 2009). "The overexpression of cyclin D1 has a significant positive correlation with hormone receptor status, non-triple negative and non-basal-like breast carcinomas suggesting that cyclin D1 expression might be a marker of good prognosis." (PMID 19615042, 2009). "Cyclin D1 had a positive correlation with ER, PR and non-basal breast carcinomas." (PMID 19615042, 2009). "Furthermore, cyclin D1 overexpression has been shown to confer resistance to antioestrogens in breast cancer cells and has been identified as a negative predictive factor for tamoxifen response." (PMID 16504004, 2006). "However, neither overexpression of cyclin D1 or of cdc25A was found to be an independent indicator of prognosis in early stage breast cancer." (PMID 11875707, 2002). "Our results that MTF2 represses CCND1 expression in MDA-MB-231 may help explain the recent reports that low MTF2 expression leads to increased chemotherapeutic resistance in leukemia and downregulation of MTF2 was correlated with poorer clinical outcomes in breast cancer." (PMID 39903505, 2025). "Similarly, the amplification of the CCND1 gene sequence or overexpression of cyclin D1 also induces cancer cell proliferation and tumorigenesis, which is frequently found in a higher proportion of human breast cancers and serves as a negative prognostic marker." (PMID 39593745, 2024). "Interestingly, tumor types that express other forms of CYCLIN D-CDK4/6 complexes, such as breast cancers in which CDK4 is often in complex with CYCLIN D1, do not undergo apoptosis or exhibit changes in the phosphorylation status of metabolic enzynes in response to CDK4 inhibition." (PMID 36051751, 2022). "Additionally, some studies have even suggested non-oncogenic role for Cyclin D1, and down-regulated Cyclin D1 could increase the cell invasion and improve the outcome of breast cancer patients." (PMID 34975298, 2022). "In spite of the fact that the mechanism is not fully defined, the lessons learned from Cyclin D1 and Cdk4 null mouse models have important implications with respect to therapeutic modalities that might be effective in the treatment of breast cancers that are HER2-positive." (PMID 36051751, 2022). "As expected, increasing LPP1 expression decreased the levels of cyclin D1 and D3, and this is most likely due to the decrease in AP-1, which could also contribute the effects of LPP1 expression in decreasing the division and invasiveness of breast cancer cells." (PMID 31534541, 2019). "In addition, when a panel of 47 human breast cancer and immortalized breast cell lines grown in vitro were treated with a CDK4/6 inhibitor (palbociclib), sensitive cell lines (estrogen receptor positive) showed increased expression of the genes RB1 and CCND1 and reduced expression of CDKN2A (p16)." (PMID 30443290, 2018). "To assess whether Kdm3a could directly promote cyclin D1 expression at the transcriptional level, we performed ChIP assay to examine if Kdm3a was recruited to the 5’ regulator sequence of the cyclin D1 gene containing the cyclin D1 promoter in MCF-7 human breast cancer cells." (PMID 29156681, 2017).
breast cancer (continued). "Protein detection showed that, in addition to inhibiting the expression of Ki67 and cyclin D1, UbcH10 RNAi also impaired the increased BCL-2 and MDR-1 expression levels in MCF-7/EPB/TXT cells, which may contribute to abating the drug resistance in the breast cancer cells." (PMID 25739083, 2015). "Similarly, mammary tumor samples derived from caveolin-1 knockouts crossed with mouse mammary tumor virus-polyoma middle T antigen [PyMT/Cav-1(-/-)] mice show ERK-1/2 hyperactivation, cyclin D1 up-regulation, and Rb hyperphosphorylation, consistent with dysregulated cell proliferation." (PMID 24236206, 2013). "It is thought that the ability of cyclin D1 to activate CDK4 is critical for driving tumorigenesis, and that CDK4-associated kinase activity is required to maintain this tumorigenesis, as shown in mice with Her2-induced, but not Wnt-1-induced and Ras-induced breast cancer." (PMID 23336272, 2013). "However, whether these estradiol-repressible miRNAs coordinately control cell proliferation and survival by targeting bcl-2, cyclin D1 and survivin at the post-transcriptional level in breast cancer cells is not fully investigated." (PMID 22260523, 2012). "In breast cancer alone, up to 50% of patients with Rbness in the absence of RB1 genomic alterations harbored amplifications in PIK3CA, RB (CCND1 and CCNE1), and ER signaling modules (ESR1, FOXA1, and GATA3)." (PMID 40138429, 2025). "The hijacked enhancers on chromosome 8 in ZR751 exhibit H3K27ac enrichment in the breast cancer cell line T47D without the translocation, but little enrichment in the B-cell lymphoma line REC1 in which CCND1 hijacks enhancers from chromosome 14." (PMID 39033128, 2024). "In primary breast cancer patient tumor samples from PCAWG, although we did not observe the same translocation event, we found that the CCND1 locus is highly subject to translocations with diverse regions of chromosome 8." (PMID 39033128, 2024). "In predominantly CDK4-dependent cells (such as estrogen receptor-positive [ER+] breast cancer), abemaciclib, ribociclib, and palbociclib displace p21 from the CDK4/cyclin D1 complex (but not CDK6 from CDK6/cyclin D1)." (PMID 37369022, 2023). "Consistently, cyclin D1 levels alone are not correlated with cell-cycle entry in vitro and therapeutic outcomes of CDK4/6 inhibitors in breast cancer patients." (PMID 36207346, 2022). "The genes FGFR2, CCND1 and TOX3 are still not studied much in relation to the roles in breast cancer although genetic studies have suggested their involvement in cancer risk." (PMID 35267517, 2022). "In the research of breast cancer, ESM1 was found to further enhance the malignant transformation of triple-negative breast cancer cells by activating the AKT/NF-κB/Cyclin D1 pathway." (PMID 36117773, 2022). "The results revealed that non-polar KYC4048 metabolites induced cell death of breast cancer cells and decreased expression levels of WNT2B, β-catenin, and Wnt target genes (c-Myc and cyclin D1)." (PMID 33746192, 2021). "Upon 16-day treatment with BI01002494 no specific increase in proliferation (cyclin D1/2, PCNA) or invadopodia (MMP14, PARP) markers is observed in either DU4475 or MDA-MB-468 breast cancer cell lines." (PMID 32292575, 2020). "We then examined the relationship between gene amplification and genome doubling in breast cancer, by comparing CCNE1, CCNE2, CCND1 and CCND2 gene amplification in non-genome doubled and genome doubled tumours." (PMID 32823571, 2020). "KLF4 also functions as an oncogene to promote proliferation of breast cancer and bladder cancer cells in the presence of RASV12-Cyclin-D1 signaling or the absence of p21CIP1." (PMID 30933982, 2019). "Unfortunately, some frequent CNAs of breast cancer (e.g., MYC, CCND1 amplification) reported previously were not included in our gene panel." (PMID 30086764, 2018).
breast cancer (continued). "Surprisingly, despite the central role of Cyclin D1 in cell cycle regulation, mice lacking Cyclin D1 are viable and resistant to HER2(neu)-induced breast cancers (but not to breast cancers induced by MYC)." (PMID 29670855, 2018). "This analysis identified 30/229 known cancer genes (T200 targeted platform) and 11/40 TCGA breast cancer genes that were differentially expressed relative to the normal breast cells, including KRAS, GATA3, CCND1, CDH1, GNAS, and several others." (PMID 28794488, 2017). "This suggests that TLK2 is frequently co-amplified with RPS6KB1, but not with other known amplified genes in breast cancer such as ERBB2, MYC, CCND1, and so on." (PMID 27694828, 2016). "Genes with recurrent amplifications in breast cancer showed 100% (ERBB2, FGFR1), 96% (CCND1), and 88% (MYC) concordance for the amplified/non-amplified status." (PMID 27028851, 2016). "In this report, cyclin D1 was co-overexpressed in nine of 14 breast cancer tissues with MST3 overexpression, but cyclin D1 expression level does not correlate to that of MST3 expression level." (PMID 26910843, 2016). "TLK2 amplification is independent of most known amplified oncogenes in breast cancer (that is, HER2, CCND1 and MYC), except RPSKB1." (PMID 27694828, 2016). "While cyclin D1/CDK4 specifically mediates centrosome amplification triggered by H-RasG12D, H-RasG12D&c-Myc, and in HER2+ breast cancer cells, silencing of cyclin E or CDK2 have no impact on centrosome amplification in the HER2/Ras systems." (PMID 23886499, 2013). "We measured cyclin D1 levels in non-irradiated MCF10A, ER-PR-HER2-, and ER-PR- HER2+ cell lines and showed that all breast cancer cell lines overexpressed cyclin D1." (PMID 23886499, 2013). "Moreover, CCND1 amplification on 11q13 has been reported to be associated with luminal subtypes, and in agreement with this we found that CCND1 and FGFR1 amplification was most frequent in the luminal B subtype whereas CCND1 amplification was absent from all of the basal-like breast cancers." (PMID 22863309, 2012). "Much like CCND1, some controversy surrounds expression patterns of ID1, and despite numerous links to invasion and migration in breast cancer some groups report an absence of the protein in the normal mammary gland." (PMID 21955753, 2011). "Cyclin D1, but not cyclin E, was decreased in isoindigo 5′-Br treated HL-60 cells 31, whereas both cyclins D1 and E were consistently inhibited in esophageal cancer cells 28, MCF-7 and T-47D breast cancer cells treated with niclosamide." (PMID 40657389, 2025). "For example, CCND1 amplifications in head and neck squamous cell carcinomas appear to be driven primarily by BFB-mediated amplification rather than by TB amplifications as observed in breast cancer." (PMID 37198482, 2023). "In agreement with the results from the cell-cycle analysis, we found that the protein expression of the negative cell-cycle regulator P21 was markedly increased in breast cancer cells after ZLM-7 treatment, which was accompanied with decreased expressions of cyclin D1, CDK2 and CDK6." (PMID 35890172, 2022). "Next, an in silico analysis showed that genes related to breast cancer, including HES1, MYC, CCND1, FOS and PGR, could be regulated by NRIP1 (data not shown)." (PMID 34707101, 2021). "Although ER+/HER2+ breast cancers are not currently eligible for CDK4/6 inhibitor therapy, preclinical data have shown that cyclin D1/CDK4/6/pRB axis may be deregulated and represent a key mechanism driving resistance to anti-HER2 therapies." (PMID 32164162, 2020).